KMT2A (lysine methyltransferase 2A)
Diseases named in the same sentence as KMT2A in open-access papers (continued):
Sharing a sentence is not in itself a finding about the gene and the disease.
pancreatic cancer (20 papers, 2011 to 2025). "For example, inhibiting HDAC6 can activate PD-L1 expression in melanoma, and abnormal KMT2A methylation promotes pancreatic cancer development." (PMID 40003691, 2025). "In pancreatic cancer, inhibition of MLL1(KMT2A)activity or silencing expression reduces H3K4me3 levels in the CD274 promoter region and downregulates PD-L1 expression." (PMID 36713412, 2022). "In addition to its role in neurodevelopment, PHF14 also forms part of another subcomplex that includes KMT2A, PHF5A, HMG20A, and RAI1, a subcomplex that epigenetically regulates pancreatic cancer stem cells through KMT2A’s methyltransferase activity." (PMID 39766920, 2024). "Moreover, a KMT2A inhibitor combined with anti-PD-L1 or anti-PD-1 antibodies can effectively restrain the growth of a mouse model of pancreatic tumor in a Fas L- and CTL-dependent manner." (PMID 36713412, 2022). "Targeting the KMT2A protein subcomplex epigenetically diminished the tumorigenic characteristic of pancreatic adenosquamous carcinomas, implying the capability for KMT2A inhibition as an adjunct to chemotherapy and eventually enhancing clinical outcomes for pancreatic cancer patients." (PMID 38791111, 2024). "Here, the authors identify the histone methyltransferase KMT2A as a binding partner of the PHF5A-PHF14-HMG20A-RAI1 protein subcomplex and an epigenetic regulator of the PCSCs characteristics and show the therapeutic potential of targeting this axis in pancreatic cancer." (PMID 37709746, 2023).
glioma (18 papers, 2013 to 2024). A benign or malignant brain and spinal cord tumor that arises from glial cells (astrocytes, oligodendrocytes, ependymal cells). "Two studies used modified U-87 glioma cells lines to characterize the role of the KMT2A-NOTCH regulatory cascade and of RECQ1 Helicase in glioma proliferation." (PMID 35706426, 2022). "KMT2A is preferentially expressed in glioma stem cells and downregulation reduces CSC self-renewal and tumorigenicity." (PMID 29728583, 2018). "Because of the advantages of rapid growth and the optical clarity of zebrafish embryos, we transplanted the KMT2A-knockdown U-87 MG cells into zebrafish brains to investigate the role of KMT2A in glioma progression in vivo." (PMID 28968975, 2017). "A previous study found that miR-769-5p promotes the growth of glioma cells through the suppression of KMT2A and could be useful as a therapeutic target for glioma treatment." (PMID 33023466, 2020). "We investigated the role of KMT2A in U-87 MG cells (grade IV glioma cell line)." (PMID 28968975, 2017). "KMT2A has an epigenetic regulation role on NOTCH1 and NOTCH3, and this mechanism is essential for inhibiting glioma proliferation." (PMID 33711952, 2021). "MOs were used to knock down lysine (K)-specific methyltransferase 2A (KMT2A), involved in glioma progression, resulting in downregulated proliferation of neural progenitors, premature differentiation of neurons and impaired gliogenesis." (PMID 33802571, 2021). "Our candidates also included several genes typically considered TSGs, including CDKN1A (bladder carcinoma, 9.2% in TCGA), KMT2A (kidney carcinoma, 0.6%), MGA (ovarian carcinoma, 1.5%), PTEN (high-grade glioma, 14.2%), RB1 (lung adenocarcinoma, 5.0%), SMAD4 (ovarian carcinoma, 0.5%)." (PMID 34313788, 2021).
melanoma (18 papers, 2015 to 2025). A malignant, usually aggressive tumor composed of atypical, neoplastic melanocytes. "The mutation in BAP1 was captured in the melanoma, as well as mutations in KMT2A (a known cancer driver mutation in melanoma) and TIAM1 (a gene involved in the RAC1 signaling pathway affecting cell shape and migration)." (PMID 35052351, 2021). "Overexpression of hTERT partially reversed the inhibitory effects caused by KMT2A knockdown on melanoma growth and tumorsphere formation, suggesting that KMT2A promoted melanoma growth in part via the hTERT pathway." (PMID 28726783, 2017). "To illuminate the underlying molecular mechanism by which KMT2A knockdown inhibited cell migration and promoted apoptosis in melanoma, we analyzed the expression of a series of migration-related proteins and apoptosis-related proteins possibly affected by KMT2A." (PMID 28726783, 2017). "Our results showed that knockdown of KMT2A inhibited cell proliferation and induced apoptosis by activating the caspase-dependent signaling pathway, KMT2A promoted cell growth via hTERT signaling, and high expression of KMT2A was associated with poor prognosis in melanoma patients." (PMID 28726783, 2017). "KMT2A and hTERT are positively correlated in melanoma tumor tissues, and KMT2A promotes melanoma cell growth by targeting the hTERT signaling pathway." (PMID 33711952, 2021). "For instance, the hub Kmt2a (lysine methyltransferase 2A) from the blue module is responsible for H3K4 methylation and associated with melanoma growth." (PMID 32831131, 2020). "KMT2A has been found to interact with the NF-κB pathway to regulate brain cancer growth and promotes melanoma growth by activating the hTERT signaling." (PMID 29728583, 2018). "To uncover the clinical significance of KMT2A and further confirm its relevance with hTERT, we detected their expression in melanoma tissue samples." (PMID 28726783, 2017). "To assess the role of KMT2A in melanoma cells, we first determined the expression levels of KMT2A in a panel of human melanoma cell lines (A375, MeWo, A431, WM35)." (PMID 28726783, 2017). "All these results from the xenograft model indicated that KMT2A knockdown indeed had anti-cancer effects in melanoma, which were at least partially achieved by activating the hTERT signal pathway." (PMID 28726783, 2017). "KMT2A was identified as a candidate target from a siRNA library screening, and we found that KMT2A knockdown inhibited cell proliferation, promoted apoptosis and suppressed the growth of melanoma xenograft." (PMID 28726783, 2017). "In this study, we have demonstrated the functional significance of KMT2A in melanoma progression in vitro and in vivo." (PMID 28726783, 2017). "Our study has not only revealed the role of KMT2A in melanoma progression for the first time, but also identified a potential therapeutic target for melanoma treatment." (PMID 28726783, 2017). "KMT2A knockdown significantly inhibited cell viability and cell migration and induced apoptosis, whereas KMT2A overexpression effectively promoted cell proliferation in various melanoma cell lines." (PMID 28726783, 2017). "Taken together, these data indicated that KMT2A promoted hTERT expression at the transcriptional level through binding to its promoter in melanoma cells." (PMID 28726783, 2017). "In this study, we identified KMT2A as a potential target, which promoted the growth of human melanoma cells." (PMID 28726783, 2017). "Further study showed that KMT2A regulated melanoma cell growth by targeting the hTERT-dependent signal pathway." (PMID 28726783, 2017). "Collectively, our clinical results validated the protumorigenic function of KMT2A in melanoma, and suggested that it was mediated through the hTERT signaling pathway." (PMID 28726783, 2017). "Correlation analysis showed that the expression of KMT2A and hTERT were positively correlated in human melanoma (P=0.0444)." (PMID 28726783, 2017).
melanoma (continued). "In keeping with our data, MECOM, MLL2 (KMT2D), MLL (KMT2A), ARID2, and CUX1 were among the most frequently mutated epigenetic genes in the TCGA and Broad Institute melanoma cohorts." (PMID 26221190, 2015). "Also, high KMT2A expression predicted poor survival in hepatocellular carcinoma, and melanoma patients, demonstrating the potential clinical benefit of KMT2A degradation in both KMT2A‐r and wild‐type patients." (PMID 39754404, 2025). "Of note, most co-occurring mutations in melanoma BRAF Class 2 and 3 (KMT2A, NOTCH1, APC) are of unknown significance, whereas those in Class 1 are amplifications and putative drivers such as NOTCH2 and MET amplifications." (PMID 38275886, 2024). "Analysis of the relationships between KMT2A expression and different clinicopathologic variables showed that the expression of KMT2A was significantly correlated with the location (P=0.0156) and the growth pattern of melanoma (P=0.0253 and 0.0064)." (PMID 28726783, 2017). "In addition, the results from a xenograft mouse model confirmed that KMT2A promoted melanoma growth via hTERT signaling." (PMID 28726783, 2017). "In addition, our clinical data indicated that KMT2A and hTERT were positively correlated and KMT2A high expression predicted poor prognosis in melanoma patients." (PMID 28726783, 2017). "Collectively, these results confirmed that KMT2A promoted melanoma cell growth." (PMID 28726783, 2017). "The protein and mRNA levels of hTERT were reduced when KMT2A was silenced, but were significantly increased when KMT2A was overexpressed, supporting that KMT2A could regulate melanoma growth via hTERT signaling." (PMID 28726783, 2017). "The oncogenic role of KMT2A in melanoma was further examined in a mouse xenograft model." (PMID 28726783, 2017). "We further investigated the prognostic role of KMT2A in melanoma patients." (PMID 28726783, 2017). "Finally, analyses of clinical samples demonstrated that the expression of KMT2A and hTERT were positively correlated in melanoma tumor tissues, and KMT2A high expression predicted poor prognosis in melanoma patients." (PMID 28726783, 2017). "Collectively, our results indicate that KMT2A promotes melanoma growth by activating the hTERT signaling, suggesting that the KMT2A/hTERT signaling pathway may be a potential therapeutic target for melanoma." (PMID 28726783, 2017). "In summary, our study has revealed a potential oncogenic role of KMT2A in melanoma." (PMID 28726783, 2017). "Moreover, overexpression of hTERT partially reversed the tumorsphere formation inhibition caused by KMT2A knockdown, suggesting that KMT2A regulated the expression of cancer stem cell markers and tumorsphere formation in melanoma via the hTERT signaling pathway." (PMID 28726783, 2017). "In addition, to determine whether knockdown of KMT2A inhibited melanoma cell growth through regulating hTERT expression, MTS assay was performed to explore if overexpression of hTERT could offset the inhibitory effect caused by KMT2A knockdown." (PMID 28726783, 2017). "Considering that KMT2A has been reported to regulate the expression of its target genes at their promoter regions, we examined whether it directly modulated the expression of genes involved in melanoma growth." (PMID 28726783, 2017). "Furthermore, high expression of KMT2A was related to poor prognosis in melanoma patients, suggesting that KMT2A could be a potential biomarker for the diagnosis and a therapeutic target for the treatment of melanoma in the future." (PMID 28726783, 2017).
myeloid neoplasm (16 papers, 2013 to 2026). Proliferation of myeloid cells originating from a primitive stem cell. "Genetic rearrangements of the KMT2A gene are associated with diagnostic and prognostic outcomes in the context of myeloid neoplasms." (PMID 38730645, 2024). "KMT2A-PTDs are intragenic gene rearrangements of clinical importance to the management of myeloid neoplasms." (PMID 38730645, 2024). "A notable contribution of OGM in characterizing myeloid neoplasms is its ability to detect cryptic chromosomal abnormalities, such as KMT2A-PTD, a cryptic intragenic alteration recognized as a high-risk molecular marker in MDS according to the IPSS-M scoring system." (PMID 40565225, 2025). "KMT2A PTD was detected exclusively in myeloid neoplasms, including AML, MDS, and CMML." (PMID 39766092, 2024). "KMT2A PTD is exclusively found in myeloid neoplasms, including AML, MDS, and CMML." (PMID 39766092, 2024). "KMT2A PTD was detected exclusively in a subset of myeloid neoplasms, including AML, MDS, and CMML." (PMID 39766092, 2024). "We summarize the current state of development for inhibitors against Menin‐KMT2A, DOT1L, KDM1A, and Polycomb complexes, and the arginine methyltransferase PRMT5 for the treatment of myeloid malignancies, lymphoma, and different solid tumors." (PMID 40181550, 2026). "Several of the recurrently detected genetic abnormalities in patients with myeloid malignancies involve epigenetic modifiers like DNMT3A, TET2, ASXL1, EZH2, IDH1/2, KMT2A, KAT6A, KDM5A, KDM6A, or NSD1." (PMID 33371192, 2020). "KMT2A fusions were the most common (n = 28, 60%, GRIN p = 1.86 × 10−74) and other in-frame fusions previously reported in myeloid malignancies involving NUP98 (n = 3) and ETV6 (n = 2) were also observed." (PMID 33579957, 2021).
Kabuki syndrome (15 papers, 2012 to 2025). Kabuki syndrome (KS) is a multiple congenital anomaly syndrome characterized by typical facial features, skeletal anomalies, mild to moderate intellectual disability and postnatal growth deficiency. "For example, 16N-0149 presented with a CHARGE-like presentation but was found to have a de novo variant in KMT2A, the gene responsible for Kabuki syndrome." (PMID 28600779, 2017). "KMT2A germinal mutations are associated to Wiedemann–Steiner syndrome and also in patients with initial clinical diagnosis of several other chromatinopathies (i.e., Coffin–Siris syndromes, Kabuki syndrome, Cornelia De Lange syndrome, Rubinstein–Taybi syndrome), sharing an overlapping phenotype." (PMID 35328068, 2022). "Paradoxically however, loss-of-function variants of KDM6A, which is an H3K4 demethylase and therefore supposedly the functional opposite of KMT2A or KMT2D, also cause Kabuki syndrome." (PMID 38370361, 2024). "Mutations of KMT2A is associated with Wiedemann-Steiner syndrome, while mutations of KMT2D is associated with Kabuki syndrome." (PMID 38370361, 2024). "It would be interesting to investigate cTfh cells in additional patients with KMT2A-associated WSS and KMT2D-associated Kabuki syndrome as this may help elucidate the underlying pathophysiology of the antibody deficiency." (PMID 28623346, 2017).
lymphoid leukemia (14 papers, 2013 to 2026). A malignant lymphocytic neoplasm of B-cell or T-cell lineage involving primarily the bone marrow and the peripheral blood. "Acute myeloid and lymphoid leukemias often harbor chromosomal translocations involving the KMT2A gene, encoding the KMT2A lysine methyltransferase (also known as mixed-lineage leukemia-1), and produce in-frame fusions of KMT2A to other chromatin-regulatory proteins." (PMID 34663924, 2021). "Since the relationship between KMT2A and both myeloid and lymphoid leukemias was first discovered, its crucial role as an epigenetic regulator has been further characterized along with the importance of other gene family members." (PMID 36479909, 2023). "The KMT2A gene, better known as MLL (mixed lineage or myeloid/lymphoid leukemia) encodes a lysine (K)-specific histone methyltransferase 2A, which functions as an epigenetic regulator of transcription." (PMID 26161385, 2015). "MLL1 (also known as MLL and KMT2A) was initiallycloned from acute myeloid and lymphoid leukemia that contain frequentMLL1 chromosomal fusions and translocations." (PMID 24172249, 2013).
colon carcinoma (13 papers, 2011 to 2025). "In particular, histone-lysine N-methyltransferase genes KMT2D, KMT2C and KMT2B in bladder, lung and endometrial cancers, whereas the KMT2A is mostly mutated in non-small cell lung cancer and colon cancer." (PMID 34302033, 2021).
glioblastoma (10 papers, 2015 to 2025). The most malignant astrocytic tumor (WHO grade IV). "In conclusion, we identified KMT2A-NOTCH as a negative regulatory cascade for glioblastoma cell proliferation, and this result provides important information for KMT2A- or NOTCH-targeted therapeutic strategies for brain tumors." (PMID 28968975, 2017). "In the current study, we examined the role of KMT2A in the U-87 MG glioblastoma cell line." (PMID 28968975, 2017). "In this study, we analyzed the role of KMT2A in the glioblastoma cell line U-87 MG." (PMID 28968975, 2017). "To assess the functional importance of SET1/MLL family complex members for glioblastoma cell viability, we performed siRNA mediated knock-down of WDR5 and KMT2A (MLL1) in U373 and U87MG cells and checked their colony forming ability." (PMID 37974198, 2023). "To address the essential role of ASH2L for glioblastoma cell survival further, we focused our attention to chromatin modifying complexes, specifically, SET1/MLL family of histone methyltransferases SET1 (SETD1A), SET1B (SETD1B), MLL1 (KMT2A), MLL2 (KMT2B), MLL3 (KMT2C) and MLL4 (KMT2D)." (PMID 37974198, 2023).
acute promyelocytic leukemia (9 papers, 2019 to 2025). An aggressive form of acute myeloid leukemia (AML), characterized by arrest of leukocyte differentiation at the promyelocyte stage, due to a specific chromosomal translocation t(15;17) in myeloid cells. "Further recurrent genetic lesions in AML relevant for this work include lysine methyl transferase 2A (KMT2A; previously known asMLL) fusion genes, partial tandem duplications withinKMT2A (KMT2A-PTD), and fusion genes between promyelocytic leukemia and retinoic acid receptor alpha (PML-RARA)." (PMID 31723419, 2019).
Intellectual disability (9 papers, 2019 to 2025). "Wiedemann–Steiner syndrome (WDSTS) is a rare autosomal dominant disorder caused by mutations in the KMT2A gene and is usually characterized by hairy elbows, short stature, developmental delay, intellectual disability and obvious facial dysmorphism." (PMID 37649104, 2023). "For example, while KDM5C is an H3K4me eraser, KMT2A is an H3K4me writer, and KMT2A haploinsufficiency is associated with the NDD Weidemann–Steiner Syndrome (WDSTS) characterized by intellectual disability, developmental delay, hairy elbows, and short stature in both males and females." (PMID 36831303, 2023). "Therefore, we predicted that the observed phenotypes were caused by the c.2318:p.S774Vfs*12 variant in KMT2A in our patient with intellectual disability, intellectual developmental delay, wide eye distance, and hypotonia." (PMID 37649104, 2023). "Interestingly, a case report on a child with intellectual disability showed both KMT2A-deletion and eosinophilia, indicating tumor suppressor gene activity for KMT2A in this malignancy." (PMID 33048949, 2020). "Because KMT2A regulates multiple Hox and Wnt related genes through histone H3 lysine 4 (H3K4) methylation, phenotypes of the WDSTS patients are complex and involve multiple systems, including craniofacial features, skeletal anomalies, organic problems, development and intellectual disability." (PMID 32311999, 2020).
lung carcinoma (9 papers, 2009 to 2023). "Metformin suppressed the protein and mRNA expressions of euchromatic histone lysine methyltransferase 1, 2 (EHMT1, EHMT2), enhancer of zeste 1, 2 polycomb repressive complex 2 subunit (EZH1, EZH2), lysine methyltransferase 2A, 2B (MLL1, MLL2), and WD repeat domain 82 (WDR82) in lung cancer cells." (PMID 33578894, 2021).
B-cell acute lymphoblastic leukemia (8 papers, 2016 to 2022). A neoplasm of lymphoblasts committed to the B-cell lineage, typically composed of small to medium-sized blast cells. "The KMT2A gene, formerly named the MLL gene, is rearranged (KMT2Ar) in 70–75% of infants, 5–6% of children and 10–15% of adult patients with B cell acute lymphoblastic leukemia (B-ALL)." (PMID 35933338, 2022).
developmental delay (8 papers, 2019 to 2025). "Large scale exome sequencing studies identified mutations in MLL1/KMT2A among patients presenting with developmental delay and ID." (PMID 36845425, 2023). "KMT2A and MED12L, involved in chromatin remodeling and transcription regulation, respectively, are essential for synaptic development and motor–speech coordination, with dysfunctions linked to developmental delays." (PMID 40870030, 2025).